IL4R (interleukin 4 receptor)
Diseases named in the same sentence as IL4R in open-access papers (continued):
Sharing a sentence is not in itself a finding about the gene and the disease.
asthma (continued). "Additionally, dupilumab, an IL4R-blocking antibody approved for the treatment of atopic dermatitis, asthma, and chronic sinusitis with nasal polyposis, showed efficacy in reducing LUADBM organoid growth." (PMID 39941924, 2025). "Thus, more high-quality systematic reviews are needed to further verify the effects of anti-IL4Rα treatment on patients with severe asthma." (PMID 40520782, 2025). "Thus, in the event of interaction between dupilumab and IL-4R, all these mechanisms are downregulated, making dupilumab a potential alternative to omalizumab in patients with allergic IgE-mediated asthma." (PMID 39997320, 2025). "IL-4Rα mAb treatment effectively inhibited CCL26 production in BECs from asthma patients." (PMID 40370530, 2025). "Additionally, high baseline CD45RO+ ILC2 levels predicted rapid and favorable responses to anti‐IL4Rα blocking antibody therapy (i.e., a biologic called dupilumab) in severe asthma patients." (PMID 40016948, 2025). "There is a possibility that IL-4R or TSLPR is induced or increased in eosinophils from patients with severe asthma or atopic dermatitis, and these eosinophils may respond to IL-4, IL-13, or TSLP at concentrations up to 10 nM." (PMID 39624446, 2024). "In atopic patients, immunological and genetic studies have outlined allergic inflammatory pathways common to several conditions, such as atopic dermatitis, asthma, and food allergy, among others, of which the central pathogenesis is the interleukin 4 receptor (IL-4R) pathway." (PMID 38493053, 2024). "Dupilumab was proven to be an efficacious inhibitor of type II inflammation by blocking IL-4Rα, thus, it could alleviate the symptoms of AD, allergic rhinitis, and asthma at the same time." (PMID 37153599, 2023). "The interleukin-4 receptor plays a pivotal role in the inflammatory response and is targeted by the drug dupilimumab, a monoclonal antibody approved to treat allergic diseases such as eczema, asthma, and nasal polyps." (PMID 35454087, 2022). "Conversely, our group reported a reduced pIgR expression in the bronchial epithelium from patients with asthma, with in vitro experiments indicating that IL-4R activation (and thus a type 2 immune environment) may account for this epithelial defect in asthma." (PMID 35386640, 2022). "Furthermore, anti-IL4R treatments reduced inflammatory cell recruitment, improved measurable lung function and decreased overall asthma symptoms in both humans and monkeys." (PMID 36353222, 2022). "Moreover, the G allele has been reported to be associated with allergic rhinitis, and to predict the drug effects of anti-interleukin (IL)-4Rα biologics in patients with asthma." (PMID 35312711, 2022). "Moreover, accumulative studies have supported the critical functions of IL-4R in asthma pathogenesis and IgE level regulation." (PMID 36910341, 2022). "Based on preclinical work, the transient increase in eosinophils observed in asthma and CRSwNP patients may be related to blockade of IL‐4Rα with dupilumab reducing eotaxin production, thus inhibiting eosinophil chemotaxis and tissue infiltration." (PMID 34037993, 2021). "Murine asthma models have demonstrated a significant reduction in airway hyperresponsiveness, lung eosinophilia, and goblet cell metaplasia upon monoclonal antibody (mAb) blockade of IL-4Rα." (PMID 33653328, 2021). "The current add-on treatment options for severe asthma are long-acting muscarinic antagonist (LAMA), leukotriene modifier, low dose azithromycin, and low dose oral corticosteroids (OCS), and biological drugs such as anti-IgE, anti-IL-5/IL-5R, or anti-IL-4R for type 2 severe asthma." (PMID 35387016, 2021). "Others think that AAM doesn’t have a significant role in the developments of asthma, supported by a study showing that deletion of macrophage IL-4Rα doesn’t affect the pathology of allergic asthma, and increased M2 cell percentage in asthma is just an association of increased Th2 response." (PMID 32024540, 2020).
asthma (continued). "This hypothesis is indirectly supported by the efficacy of dupilumab, which inhibits both IL-4 and IL-13 signaling mediated by IL-4Rα, in patients with severe uncontrolled asthma." (PMID 31866859, 2019). "This protective effect against infections has been observed also for other type 2 immune diseases when treated with biologics targeting the IL-4R complex, such as the anti-IL-13 antibody Lebrikizumab in asthma and AD and the IL-4Rα-blocking agent Pitrakinra in asthma." (PMID 31708926, 2019). "Therefore, inhibitors directed against IL-13 or IL-4Rα have been developed as new asthma therapeutics." (PMID 30500834, 2018). "IL-4Rα Q576R, which can affect the binding of IL-4 and phosphorylation of intracellular substrates including signal transducer and activator of transcription 6 (STAT6), has been linked to many autoimmune disorders such as asthma, atopy, and allergy." (PMID 28511637, 2017). "Because, for example, inhaling soluble IL-4R (altrakincept) was effective in the treatment of moderate asthma in patients, this biological may represent a candidate to medicate TB tissue pathology." (PMID 26977119, 2016). "Neutralizing antibodies to IL-4Rα and IL-13, such as dupilumab and lebrikizumab, respectively, do show promise in clinical effectiveness but only in select patients with typical Th2-type asthma." (PMID 26635789, 2015). "Moreover, the allergic airway disease model has been in use for over 20 years and predicted the successful outcomes of asthma clinical trials involving anti-IL-13 and anti-IL-4Rα antibodies." (PMID 26605551, 2015). "The type 1 immune response-driving potential of IL-4Rα in the early phase of pulmonary infection may be exploited in vaccination strategies against Th2-related pulmonary infection and possibly also in asthma." (PMID 24475277, 2014). "In this study, we have comprehensively analyzed the association of 286 common variants of eight candidate genes with asthma and atopic asthma in a case-control Spanish sample and found associations for 10 SNPs in three of them (MS4A2, IL4R and ADAM33) after considering all tests performed." (PMID 24039878, 2013). "To test this new model, we focus on one asthma candidate gene, the IL4R gene." (PMID 23286427, 2013). "Other genetic regulatory mechanisms beyond DNA sequence variation may aid in explaining the role of IL4R in asthma." (PMID 23286427, 2013). "IL-4Rα has been shown to play a pivotal role in the pathogenesis of Th2 inflammation and asthma." (PMID 23922687, 2013). "To explore a new model, we focused on one asthma candidate gene, the IL-4 receptor (IL4R)." (PMID 23286427, 2013). "However, several groups showed that IL-4Rα-/- mice have greatly reduced asthma like symptoms, even when purified TH2 cells were provided exogenously." (PMID 22292924, 2012). "Soluble IL-4 receptors (sIL-4R) that act as IL-4R antagonists have also been developed, they are effective in an animal model of asthma and a single nebulised dose of sIL-4R prevents the fall in lung function induced by glucocorticoid withdrawal in moderate/severe asthmatics." (PMID 18315837, 2008). "Additionally, because IL-4Rα is expressed on different lung structural cells, it will be important to verify whether dupilumab use can also impact lung remodeling, a feature of asthma." (PMID 41145900, 2025). "Biologics targeting T2-driven immune responses, including dupilumab (anti-IL-4Rα monoclonal antibody), represent a significant advancement in the management of asthma, especially for patients with moderate-to-severe disease where standard treatments may not provide adequate control." (PMID 40370530, 2025). "Furthermore, research on type-2 phenotype asthma and COPD among the Japanese population indicates that IL4R (rs8832A > G), associated with IL-4Rα levels and frequent exacerbations, may predict the effectiveness of IL-4Rα antagonist drugs." (PMID 40313547, 2025).
asthma (continued). "Indeed, the European Academy of Allergy Asthma & Clinical Immunology (EAACI) position paper on clinically applicable biomarkers for asthma cites FeNO as the best biomarker to guide anti-IL4Rα-targeted (endotypic) therapy, which was evaluated following the SAVED approach." (PMID 38711495, 2024). "Moreover, blockade of IL4Rα is a highly effective treatment for moderate to severe asthma." (PMID 39197446, 2024). "The Global Initiative for Asthma (GINA) recommends the corticosteroid, azithromycin, anti-IL4R, anti-thymic stromal lymphopoietin, long-acting muscarine anticholinergic, short-acting β-agonists, and anti-IgE antibody omalizumab for the treatment of severe asthma." (PMID 37245015, 2023). "Interestingly, the same biologics—namely anti-IgE, anti–IL-5, and anti–IL-4Rα–have been recently approved for the treatment of severe CRSwNP (while dupilumab was approved first in severe CRSwNP, before asthma), further increasing the relevance of integrating UAD in the management of (severe) asthma." (PMID 37035303, 2023). "Moreover, the efficacy of a humanized monoclonal antibody against IL-4Rα (dupilumab) in the treatment of severe T2-high asthma and CRSwNP validates the biological importance of IL-4Rα–inducible products in disease pathophysiology, although the relative contributions of each remain less clear." (PMID 34981786, 2022). "IL-4 has a pivotal role in asthma Th2-mediated inflammation and its functions are mediated by the interaction with two receptors: IL-4R type I (composed of the IL-4Rα and the common cytokine receptor γc-chains) and type II (composed of the IL-4Rα and IL-13Rα1 chains)." (PMID 33925009, 2021). "Importantly, we demonstrated that prophylactic or therapeutic use of a mAb that blocks IL-4Rα signalling, a clinically approved intervention strategy for moderate to severe asthma, can reduce the severity of inflammation and pathology related to pH1N1 infection." (PMID 33653328, 2021). "We hypothesized that interactions between genetic variants and methylation in genes in this pathway (IL4, IL4R, IL13, GATA3, and STAT6) influence asthma risk, that such influences are age-dependent, and that methylation of some CpG sites changes over time in accordance with asthma transition." (PMID 24735657, 2014). "Furthermore, IL-4Rα-targeted antibodies could reduce lung inflammation, airway hyper-­responsiveness and goblet-cell hyperplasia in mouse models of asthma." (PMID 23922687, 2013). "The targets of the FEO‐03 network, IL13, and functional partners IL13RA1, IL13RA2, IL4R, IL6, and TNF were presented in a red box from the asthma diagram of KEGG Pathways." (PMID 40777200, 2025). "Intriguingly, the clinical success of IL-4 pathway inhibitors (such as dupilumab, which blocks IL-4Rα, or various JAK inhibitors) in managing Th2-driven inflammatory diseases like atopic dermatitis and asthma provides a compelling precedent." (PMID 40864740, 2025). "In a TSLP/OVA-induced asthma model with transgenic human TSLP, TSLP receptor, IL-4, and IL-4Rα mice, the BsAb reduced every single allergic/inflammatory hallmark, while the single target blockade antibody failed to have such comprehensive effects." (PMID 41294800, 2025). "For instance, bispecific monoclonal antibodies like IBI 3002 (targeting IL-4Rα and TSLP) and lunsekimig (targeting TSLP and IL-13) aim to address both T2 and non-T2 inflammation in asthma." (PMID 40004611, 2025). "DupixentTM is an antibody directed against the α subunit of the interleukin 4 receptor (IL-4R-α), and the TezsipreTM blocks thymic stromal lymphopoietin (TSLP), which plays a key role in asthma." (PMID 36140426, 2022). "Here we therefore aim to appraise the available evidence for the effect of anti-IgE, anti-IL5 (Rα), anti-IL4Rα, anti-TSLP and anti-IL33 biologics on small airways disease in patients with severe asthma." (PMID 36239786, 2022).
asthma (continued). "The biologic drugs currently available (anti-IgE, anti-IL4Rα, anti-IL5, and anti-IL5Rα) for severe asthma are currently undergoing clinical development studies to extend their availability to patients with nasal polyposis." (PMID 35743736, 2022). "Therapies targeting mast cell mediators and/or their receptors, including monoclonal antibodies targeting IgE, IL-4/IL-13, IL-5/IL-5Rα, IL-4Rα, TSLP, and IL-33, have been found safe and effective in the treatment of different phenotypes of asthma." (PMID 36430941, 2022). "For asthma loci with a single TWAS gene, consistency was observed for RERE on 1p36, CLEC16A on 16p13, and IL4R on 16p12." (PMID 34103634, 2021). "One asthma exacerbation requiring OCS occurred in each the anti‐IgE and anti‐IL4R group and one CRSwNP exacerbation in the anti‐IL5/R group." (PMID 34331521, 2021). "Clinical trials using a humanized mAb targeting IL-4Rα have demonstrated up to 87% reduction in exacerbation rates and a 320 mL increase in FEV1 in patients with moderate to severe asthma." (PMID 33653328, 2021). "Interleukin-13 (IL13) has recently emerged as a primary target for asthma therapy, with ongoing clinical trials targeting IL13 or approved therapeutics targeting its receptor interleukin-4 receptor α (IL4Rα)." (PMID 34305924, 2021). "TWAS genes of known biological interest in asthma include IL1RL1 on 2q12, TLR1 on 4p14, TSLP on 5q22, SMAD3 on 15q22-q23, and IL4R on 16p12." (PMID 34103634, 2021). "Prioritization of druggable genes reveals known (IL4R, TSLP, IL6, TNFSF4) and potentially new therapeutic targets for asthma." (PMID 34103634, 2021). "Focussing on genes of the Th2 pathway (IL4, IL4R, IL13, GATA3, STAT6), the authors demonstrated that the odds of asthma tended to decrease at the age of 10 years with increasing GATA3 methylation." (PMID 26052354, 2015). "Vice versa, transgenic overexpression of CREMα selectively in T cells results in reduced IL-2 expression, decreased pSTAT5 and IL4R levels and diminished TH2 type cytokines in vitro and in an asthma model in vivo." (PMID 26459392, 2015). "Asthma is believed to have a strong genetic background, and hundreds of genes have been identified to be related with asthma, including GSTM1, IL10, CTLA-4, SPINK5, LTC4S, IL4R, and ADAM33." (PMID 24790987, 2014). "As would be expected, IL-4Rα-/- mice and STAT6-/- mice also have greatly reduced asthma like symptoms in response to allergen challenge." (PMID 22292924, 2012). "Secondly, Using RP, we report for the first time an interaction of six genes affecting European ancestry pediatric asthma: rs2243250 (IL4), rs6597 (STUB1) rs11168070 (ADRβ2), rs3024676 (IL4Rα), rs638376 (IL13Rα2) and rs3806446 (CHIA)." (PMID 21387019, 2011). "A human monoclonal antibody against IL4Rα, AMG317 (NCT00436670, by Amgen, Thousand Oaks, CA) has completed phase II investigation on safety and efficacy in subjects with moderate to severe asthma." (PMID 23283176, 2011). "Adoptive transfer of wild type TH2 cells into mice is an effective tool to bypass the role of STAT6 and IL-4Rα in TH2 cell differentiation, while allowing the study of these signaling molecules in the effector phase of asthma." (PMID 22014099, 2011). "At least one positive SNP with a TDT of p < 0.05 for asthma or total IgE and calcidiol or calcitriol was seen in IL10, GC, IL12B, CYP2R1, IL4R, and CYP24A1." (PMID 16600026, 2006). "Unlike T2-high asthma, which benefits from anti-IgE, anti-IL-5, and anti-IL-4Rα biologics, non-T2 asthma lacks effective biologics and is often refractory to corticosteroids." (PMID 41601686, 2026). "Dupilumab, a human mAb that binds to IL-4Rα, inhibits both IL-4 and IL-13 signaling and reduces asthma exacerbations, decreases oral corticosteroid (OCS) dosage, and improves lung function and symptom control in patients with asthma." (PMID 40810090, 2025).
asthma (continued). "We performed an in‐depth appraisal of indirect head‐to‐head comparisons of biologics approved for asthma, including anti‐IL5/5Rα (mepolizumab, benralizumab), anti‐IL4Rα (dupilumab), anti‐TSLP (tezepelumab) and anti‐IgE (omalizumab), which was neither a systematic review nor a meta‐analysis." (PMID 40156481, 2025). "This umbrella review indicated that anti-IgE treatment, anti-IL5/5Rα treatment, anti-IL4Rα treatment, and anti-TSLP treatment may be beneficial to patients with severe asthma." (PMID 40520782, 2025). "Notably, two of the identified genes are targets of known asthma drugs (i.e., TSLP [Tezepelumab] and IL4R [Dupilumab])." (PMID 39628479, 2024). "Dupilumab is an IgG4 human monoclonal antibody (mAb) that binds IL-4Ra with subsequent inhibition of IL-4R signaling induced by both IL-4 and IL-13, and down-regulation of TH2 inflammation in a variety of allergic disorders, including atopic dermatitis, asthma, and possibly other allergic diseases." (PMID 36846564, 2023). "Since our study only covered patients that had been diagnosed before 2015, newer asthma medications that directly target the IL4/IL13/IL4R pathway such as dupilimab are not involved." (PMID 37860183, 2023). "Dupilumab is a fully human anti-IL-4Rα monoclonal antibody approved by both the European Medicines Agency (EMA) and the US Food and Drug Administration (FDA) for the treatment of uncontrolled severe asthma." (PMID 37199256, 2023). "Additionally, inhaled versions of IL4Rα and TSLP fragments are in early-stage clinical trials and potentially offer alternative asthma treatment to ICS." (PMID 37265457, 2023). "Pitrakinra, targeting the α subunit of IL-4R, thereby blocking signaling of IL-4 and IL-13, suffered from similar problems to early mepolizumab trials by testing in unselected asthma populations with no clinical efficacy." (PMID 37265457, 2023). "Expression of IL-4Rα in non-hematopoietic cells contributed to other diseases including asthma, cancer, and hepatitis." (PMID 34302121, 2021). "There is previous proof of concept for this e.g., the prevention of asthma exacerbation by the IL4R antagonist, pitrakinra was shown to be effective in carriers of specific IL4R genotypes, although the specific mechanism is not known at this time." (PMID 35386986, 2021). "Ultimately, therapies targeting development of Th2 cells, such as those blocking the IL-4Rα or the cytokine TSLP, may prove the most effective in reducing persistence of asthma symptoms." (PMID 33076829, 2020). "Our study contributes to already existing literature on the central role of IL‐4Rα subunit in allergic asthma and may guide currently ongoing phase III clinical trials targeting IL‐4Rα in various asthma endotypes." (PMID 31782803, 2020). "We, thus, conclude that abrogation of IL‐4Rα signaling after allergic sensitization would have significant therapeutic benefit for TH2 type asthma without inducing potentially detrimental TH17 responses." (PMID 31782803, 2020). "Although T cells commonly contribute to the severity of asthma, they appeared to play a nonsignificant part in the exacerbation of airway hyperreactivity and remodeling in the absence of IL-4Rα signaling on Tregs." (PMID 32931477, 2020). "Type 2‐targeting biologics such as anti‐IgE, anti‐IL4Rα, anti‐IL5, and anti‐IL5Rα have entered the market for selected pheno/endotypes of asthma patients and may soon also become available for CRSwNP patients." (PMID 31090937, 2019). "Since IL-13 uses the type II IL-4 receptor, which is comprised of IL-4Rα (CD124) and IL-13Rα (CD213a), the efficacy of Dupliumab supports the notion that IL-13 may be the more important cytokine in terms of asthma pathology." (PMID 31120919, 2019). "AMG317, a humanized IL4Rα antibody was abandoned after phase II clinical trial because of the non-efficacy in asthma treatment." (PMID 28927416, 2017).